CCR2 (C-C motif chemokine receptor 2)
Diseases named in the same sentence as CCR2 in open-access papers (continued):
Sharing a sentence is not in itself a finding about the gene and the disease.
tumor (continued). "CCR2-positive monocytes are attracted to the LUSC tumor microenvironment in response to signals from cancer-associated fibroblasts via CCL2, contributing to an immunosuppressive environment." (PMID 38962009, 2024). "recently demonstrated that the simultaneous blockade of IL-6 and C-C motif chemokine receptor 2 (CCR2) enhanced the anti-tumor activity of NK cells in HNSCC." (PMID 39411143, 2024). "The chemokine receptor CCR2 is mainly expressed by circulating monocytes, which can differentiate into TAMs after infiltrating into the tumor stroma." (PMID 39068459, 2024). "One such therapy is a combination of two immunotherapies: the immune checkpoint inhibitor, anti-PD-1, and a CC-chemokine receptor-2 (CCR2) antagonist that prevents the tumor-induced recruitment of immunosuppressive myeloid-derived suppressor cells (MDSCs)." (PMID 39185154, 2024). "This axis involves CCL2, predominantly produced by peripheral blood mononuclear cells and tumor cells, and CCR2, mainly expressed in monocytes and macrophages." (PMID 39201480, 2024). "The CCL2/CCR2 axis mediates TAM infiltration, while the application of a natural CCR2 antagonist decreased the number of TAMs in the tumor stroma and shifted them towards the M1-like phenotype, further elevating the number of CD8+ T cells." (PMID 38787372, 2024). "Monocytes are recruited to tumor sites via CCR2 signaling, where tumor cell-secreted TGF-β induces CXCR4, stimulating them to migrate toward CXCL12-expressing perivascular cancer-associated fibroblasts (CAFs)." (PMID 39516356, 2024). "It was evident that IRF‐score is strongly associated with multiple chemokines and receptors in 12 tumours, in particular CCL5, CCR2/4/5, CXCL9/10/11 and CXCR3 (p < 0.05)." (PMID 38130025, 2024). "In a mouse model of breast cancer, MDSCs features included several genes related to immunomodulation, such as arginase 2 and Cd84, and chemokine receptors (e.g., Ccr2 and Cxcr2), suggesting that MDSCs can be directed into tumor tissue by chemokines." (PMID 38609997, 2024). "A CCR2 antagonist is a small molecule which targets the CCL2/CCR2 signaling pathway to prevent the recruitment of CCR2-expressing monocytes and macrophages to the tumor site." (PMID 39307417, 2024). "TAMs can originate from both circulating Ly6C+CCR2+ monocytes and resident tissue macrophages (RTMs) close to the tumor, as has been demonstrated in the context of gliomas and pancreatic malignancies." (PMID 38185636, 2024). "In this study, B16 tumor-derived GM-CSF expanded CCR2+ M-MDSCs in tumors, which suppressed tumor infiltration of tumor antigen-specific CD8+ T cells." (PMID 38786066, 2024). "Targeting the CCL2/CCR2 axis has previously been shown to inhibit HCC tumour growth and metastasis by reducing monocyte and TAM infiltration and increasing CD8+ T-cell cytotoxic activity." (PMID 39684877, 2024). "CCR2+ TAMs, which possess a more angiogenic phenotype, are largely present in the dense stromal margins of HCC tumours and are associated with more vascular areas." (PMID 39684877, 2024). "Depletion of CD11b+ Ly6Chigh monocytes post diphteria toxin injection in a CCR2-dependent diphteria toxin receptor (CCR2-dtx) transgenic mouse model rescued the effects of MI onto tumour growth, metastasis formation and immunosuppression." (PMID 39340596, 2024). "CCR2-expressing cells like myeloid-derived suppressor cells (MDSCs) aid in immune suppression at the tumor site." (PMID 39307417, 2024). "The CCL2/CCR2 chemokine axis is known to facilitate the migration of M-MDSCs to tumor sites, cultivating an immunosuppressive microenvironment." (PMID 38756774, 2024). "Mg transition toward CD45high and CCR2+ TAM states in the tumor core was further detected by flow cytometry." (PMID 38566128, 2024). "This is in line with the consensus in the field that tumor-associated macrophages are derived primarily from circulating blood monocytes, and in human HCC, tumor-associated macrophages arise from CCR2+ monocytes." (PMID 39761010, 2024).
tumor (continued). "Chemokine-targeted therapies impact tumor-infiltrating cells, as shown by CCR2+ cell data in mouse models." (PMID 38360737, 2024). "For example, in lung squamous cell carcinoma, CCR2 + monocytes are induced to migrate toward the tumor site by CAFs-secreted CCL2 and are then reprogrammed to M-MDSCs." (PMID 38609997, 2024). "In some mouse tumor and metastasis models, CCR2 antagonists synergize with anti-PD-1 therapy to show an enhanced antitumor response." (PMID 38338674, 2024). "Earlier findings in mice identified the key role of CCL2 in recruiting CCR2+ monocytes to metastatic sites, where they promote the extravasation of tumour cells and facilitate tumour metastasis." (PMID 38903497, 2024). "Monocytes are recruited to the tumor microenvironment via the CCR2/CCL2 axis, which has emerged as a potential target in approaches to slow cancer progression." (PMID 39545417, 2024). "In the advanced stage of HCC, CCR2 inhibits anti-tumor immune responses by recruiting and activating immunosuppressive cells, such as the macrophages, myeloid-derived suppressor cells, and regulatory T cells, thereby promoting immune escape of HCC cells." (PMID 38874512, 2024). "Cross-talk between tumor cells and TAMs is mediated by Ccl2/Ccr2 expression in the TIME, which is responsible for remodeling of the extracellular matrix, cancer progression, evasion of immunosurveillance, and angiogenesis." (PMID 38592450, 2024). "In tumor cells with low SLAMF7 expression, using a CCR2 antagonist to inhibit the CCL2/CCR2 axis, generates a greater anti-tumor impact when combined with PD-1 antibody." (PMID 39223632, 2024). "This polarization diminishes phagocytosis and fosters tumor growth via the CCL2/CCR2 axis, with the suppression of these exosomes proving more efficacious in hindering tumor progression than radiotherapy alone in a zebrafish model." (PMID 38534769, 2024). "Macrophage depletion via CCR2 blockade led to compensatory influx of neutrophils into the tumor, and only blockade of both cell types led to initiation of a tumor-directed immune response." (PMID 39335132, 2024). "We show that unlike N-NCMs, I-NCMs migrated into both vascular and extravascular tumor microenvironments via the CCR2/CCL2 axis, where they released CCL6 to recruit NK cells that promote tumor lysis, independent of T and B lymphocytes." (PMID 39545417, 2024). "In the present study, by integrating scRNA-seq data with TCGA HNSCC dataset, we identified five enriched pathways, including IL6/IL6R and CCL2/CCR2 signaling, within NK cells and tumor cells in the HPV − HNSCC cohort compared to the HPV + counterpart." (PMID 38468260, 2024). "These inhibitors show promise based on CCR2's role in cell migration to inflammation and tumor sites." (PMID 39014433, 2024). "CCL2 polarizes macrophages toward the pre-tumor phenotype by binding to the surface of macrophages through the C-C chemokine receptor 2 (CCR2)." (PMID 38655133, 2024). "Circulating M-MDSCs infiltrate tumors via the CCL2/CCR2 axis and differentiate into M2-type TAMs44; this cell population plays a pivotal role in assisting tumor growth by suppressing T cell functions and promoting angiogenesis." (PMID 38402307, 2024). "Based on this, we assessed the therapeutic efficacy of double blockade of IL6 and CCR2 signaling in orthotopic tumor models." (PMID 38468260, 2024). "In particular, CCR2+ myeloid cells are recruited into the tumor bed and a CD4+ T cell-mediated response stimulates macrophages to clear pre-malignant SnCs." (PMID 38561826, 2024). "By driving monocyte chemotaxis, the chemokine receptor CCR2 shapes inflammatory responses and the formation of tumor microenvironments." (PMID 38014122, 2024). "Macrophages are recruited to tumor sites primarily through the CCL2/CCR2 axis and CSF-1/CSF-1R signaling, so blocking these two signaling axes also reduces macrophage infiltration." (PMID 38464516, 2024).
tumor (continued). "Monocytes are recruited to the tumor site through CCL2/CCR2, inhibiting CD8+ T cell infiltration and recruiting regulatory T cells (Tregs)." (PMID 39253716, 2024). "The chemotactic cytokine ligan 2 (CCL2)-chemokine (C-C motif) receptor 2 (CCR2) axis activates tumor cell metastasis and regulates the recruitment and polarization of immune cells, affecting cancer progression and recurrence." (PMID 39138521, 2024). "These cells have been described to be pro-inflammatory in function and are recruited to tumor tissue in response to CCL2/CCR2 signaling." (PMID 38444857, 2024). "This dual role presents a paradox: while CCR2 is expected to aid in cancer prevention through its pro-inflammatory action, it can also inadvertently support tumor progression in certain contexts." (PMID 38755605, 2024). "In fact, the CCL2/CCR2 signaling axis plays a crucial role in cancer development by facilitating the proliferation and invasion of tumor cells and recruiting immunosuppressive cells, thus representing a significant opportunity for targeted therapy." (PMID 39376728, 2024). "As such the splenic red pulp acts as an extra reservoir of immunosuppressive TAM and TAN precursors (recruitment to tumor via CCR2) that promote solid tumor progression and metastasis." (PMID 39148724, 2024). "TAMs are derived from monocytes in the bone marrow, and a variety of cytokines and chemokines can direct the migration of monocytes to the tumor site, the growth of tumors can also result in the transformation of CCR2+ monocytes into TAMs." (PMID 39654890, 2024). "As expected, dual IL6 and CCR2 blockade reduced the tumor burden in an orthotopic mouse model of HPV − tumors more efficiently than either agent alone." (PMID 38468260, 2024). "The co-administration with a CCR2 inhibitor markedly enhances the tumor suppression induced by cGAMP and radiation therapy, leading to prolonged survival in tumor-bearing mice models." (PMID 38523155, 2024). "The interplay between UPP1high tumor cells and SPP1+ macrophages was linked with a variety of chemokines, including CCL2_CCR2, CCL3_CCR5, CXCL3_CXCR2, and CXCL8_CXCR1, as well as interactions such as IL1B_IL1_receptor and TGFB1_TGFbeta_receptor1." (PMID 38331898, 2024). "CCL2 is a C-C chemokine ligand produced mainly by activated T cells and plays an important role in tumor progression by activating the host pro-tumor phenotype after binding to the classical CCR2." (PMID 39350256, 2024). "Previous studies have reported that CCL2 binds mainly to its receptor, CCR2, to recruit and activate TAMs, which invade tumor sites and promote tumor progression." (PMID 38741887, 2024). "With regard to this, a high number of TAM and TAN precursors physically migrated from the spleen to the tumor stroma, and CCR2 signaling is involved in the recruitment of tumor-promoting spleen-derived TAMs." (PMID 38935134, 2024). "The regulation of chemokines has been discussed in several studies, such as the CCL2/CCR2 axis, which promotes the trafficking of monocytes/macrophages into tumor tissues." (PMID 39582864, 2024). "Cancer cells release CCL2 into the circulation, which recruits tissue macrophages and CCR2-expressing Ly6Chi monocytes to the tumor site, where they differentiate into TAMs, thereby increasing the number of TAMs within the TME." (PMID 39350256, 2024). "CCL2 was responsible for tumor recruitment of CCR2+ MDSCs and CCR4+ Tregs, suggesting the critical role of CCL2 in the generation of an immunosuppressive TME." (PMID 38786066, 2024). "In the pancreatic mouse cancer model, the combination of CCR2 antagonist with anti-PD1 antibody therapy reduces the tumor growth, while single anti-PD1 antibody-mediated therapy is not successful." (PMID 36109471, 2023). "The chemokine CCL2 and its receptor CCR2 have been shown to play multiple roles in tumorigenesis and tumor cell metastasis." (PMID 36374225, 2023).
tumor (continued). "The EDMCs in the HCC TME were induced and chemoattracted from circulating CCR2+CD45+EPCs by macrophages in the tumor tissue." (PMID 37649603, 2023). "Our study demonstrated that low expression of CDK5RAP3 promotes CCL2/CCR2 signalling to regulate the recruitment of monocytes and macrophages to tumour tissues." (PMID 35999359, 2023). "In the context of tumors, CCL2 produced by tumor cells and/or tumor stromal cells is released into the circulation and engages with CCR2 expressed on monocytes." (PMID 37108657, 2023). "Splenomegaly was also reduced in Ccl2-/- mice and Ccr2-/- mice, likely reflecting the smaller tumor size in those mice." (PMID 37208442, 2023). "In the immune evasion phase, inflammatory CCR2+ PDL-1+ monocytes with immunosuppressive properties were recruited into the tumor leading to suppression of DIVA2-induced tumor-reactive T cells." (PMID 37849753, 2023). "Selective targeting of CCR2 inhibited tumor growth and invasion, elevated the infiltration of CD8+ T cells, decreased the infiltration of M2 macrophages and decreased angiogenesis." (PMID 37208442, 2023). "Blocking the SCF-1α-CCL2 axis inhibits the recruitment of CCR2+ macrophages into tumor tissues and further suppresses the metastasis of tumor cells." (PMID 36593475, 2023). "Coculture studies also indicated that CCR2-induced stromal cell recruitment was important for tumor cell proliferation and invasion." (PMID 37208442, 2023). "CRISPR‒Cas9 gene mutation of CCR2 in MCF10CA1d cells inhibited tumor growth and TAM recruitment, which was also observed by Ccr2 shRNA knockdown in the mouse 4T1 TNBC model." (PMID 37208442, 2023). "Proinflammatory macrophage-derived LEV exhibit tumor tropism dependent on the CCL2/CCR2 signaling axis and promote drug delivery via SNARE-mediated membrane fusion in contrast to SEV." (PMID 37569508, 2023). "In contrast, Ccr2–/– tumor-bearing mice remained sensitive to E. coli–sgMafB/c-Maf treatment, indicating that monocytes and their macrophage derivatives were dispensable for this profound antitumor effect." (PMID 36821387, 2023). "Recent studies have provided compelling evidence that targeted inhibition of CCL2/CCR2 with specific drugs can effectively suppressed the recruitment of TAMs and impede tumor progression and metastasis in lung, liver, and breast cancer models." (PMID 37654704, 2023). "CCL2 binds to the homologous receptor CCR2, a signaling pair that has been shown to have a variety of protumorigenic effects, from mediating tumor growth and angiogenesis to recruiting and usurping host stromal cells to support tumor progression." (PMID 37880682, 2023). "The growth of tumor tissue can also induce CC chemokine receptor 2 positive (CCR2+) monocytes to differentiate into TAMs." (PMID 37654704, 2023). "CCR2 is a chemokine receptor expressed by a wide range of immune cells but also by different types of tumor cells." (PMID 37478172, 2023). "Tumor-infiltrating leukocytes display a high CCR2 as well as Ly6C expression on monocytes during immune evasion independent of treatment indicating a monocyte derived-MDSC (M-MDSC) phenotype." (PMID 37849753, 2023). "While this is suggestive of the immunosuppressive capacity of the CCR2+ monocytes, this combined approach appears to be insufficient to completely stop tumor growth." (PMID 37849753, 2023). "Cells expressing the CCL2-receptor CCR2 on their cell surface can migrate along a CCL2 gradient to the peripheral tumor site." (PMID 37849753, 2023). "Tumor cells recruit monocytes expressing its receptor CCR2 by releasing chemokines such as CCL2 and activating them into M2-like TAM." (PMID 37138860, 2023). "Previous study has shown that radiotherapy can activate STING/type I interferon pathway of tumor cells to enhance suppressive inflammation in TEM by recruiting myeloid cells in part via the CCR2 pathway." (PMID 37268941, 2023).
tumor (continued). "Pre-clinical models targeting the CCR2/CCL2 axis have already revealed an impact on tumor growth by blockade of CCR2/CCL2 binding." (PMID 37849753, 2023). "Systemic inflammation of primary tumor drives CCR2+Ly6C+ monocytes’ migration into lung PMN and differentiation into MAMs." (PMID 36976637, 2023). "This is most likely due to the transient depletion of CCR2+ cells that reappear in peripheral blood shortly after ceasing the antibody treatment or tumor intrinsic adaptions alleviating the need for the CCR2/CCL2 axis." (PMID 37849753, 2023). "We further clarified if this anti-tumoral effect was due to depletion of tumor promoting CCR2+ monocytes or rather to an altered T cell immune response." (PMID 37849753, 2023). "Subsequently, we adoptively transferred Bambi-KD or BAMBI-overexpressing MDSCs (CD45.1) into MC38 tumor–bearing Ccr2-KO mice (CD45.2), in which radiation-induced MDSC infiltration is absent." (PMID 38099498, 2023). "Metastasis-associated macrophages (MAMs), originating from monocytes that express CCR2, are known to contribute to the extravasation of tumor cells." (PMID 36674955, 2023). "The CCR2/CCL2 axis is a known contributor to tumour cell survival and invasion, angiogenesis, and the recruitment of immune cells." (PMID 37170733, 2023). "In the primary tumor that developed after tumor cell transplantation, CD11b+Gr1-Ly6C- resident monocytes were preferentially recruited, whereas CD11b+Gr1+Ly6C+CCR2+ inflammatory monocytes (IMs) were preferentially recruited to pulmonary metastases." (PMID 37208442, 2023). "Previous studies have shown that the CCL2/CCR2 axis is a critical chemokine signaling pathway that creates the tumor microenvironment through the recruitment of immunosuppressive cells." (PMID 36810973, 2023). "Although TAMs are mostly derived from circulating CCR2+ monocytes, it is known that they can proliferate within the tumor site and that tissue resident macrophages (i.e. KCs) can contribute to the TAM pool, as well." (PMID 36845555, 2023). "Regarding angiogenesis, our field of our interest, a previous report showed that CCR2 was involved in tumor‐promoting angiogenesis and induction of resistance to antiangiogenic therapy." (PMID 36810973, 2023). "In this study, a subset of iCAFs that expresses high levels of the chemokine CCL2, known as ICAM1+ iCAFs, was identified and was found to recruit MDSCs (THBS1+ monocytes) to hypoxic tumor areas by binding to the receptor CCR2." (PMID 37743226, 2023). "Since the monocytes were detectable in the blood about 24 h after the last injection, these findings suggest that the CCR2+ monocytes exhibit a tumor-promoting effect, which unfolds again when the depletion effect runs out." (PMID 37849753, 2023). "CCL2 is over-expressed in CRC, along with its main receptor CCR2 boosts the progression of cancer by promoting proliferation, survival, angiogenesis, migration, and invasion and contributes to tumor metastasis." (PMID 37325423, 2023). "Cytokine analysis of tumor spheroid culture media also showed that treatment with anti-CSF-1R Ab or CSF1R/CCR2/TGF-β Ab resulted in reduced release of monocyte chemoattractant proteins CCL2 and CCL7 by 231 TFM spheroids." (PMID 38076998, 2023). "In cluster 4, which mostly existed in the gem group, cells expressed high levels of CCR2, CCL2, and S100A4 genes that are associated with tumor progression and metastasis." (PMID 37324492, 2023). "Although primary tumors developed in all three mouse strains, the growth of the primary tumor was significantly delayed in Ccl2-/- and Ccr2-/- mice compared with WT mice." (PMID 37208442, 2023). "Thorough analysis of the induced TME identifies immunosuppressive CCR2+ monocytes as important counterparts of antigen-specific T cells limiting their anti-tumor capacity." (PMID 37849753, 2023).